CD69 (CD69 molecule)
Diseases named in the same sentence as CD69 in open-access papers (continued):
Sharing a sentence is not in itself a finding about the gene and the disease.
colitis (continued). "Meanwhile, CD69 has the ability to enhance the immunosuppressive function of Tregs and to alleviate colitis by improving IL-10 production." (PMID 35565775, 2022). "Albeit IFNγ expression was increased in CD69−CD103− and CD69+CD103+ CD4+ T-cell subsets during DSS-induced colitis, only small percentages of CD69−CD103− CD4+ T cells and CD69+CD103+ CD4+ TRM cells expressed IFNγ." (PMID 35844584, 2022). "During the induction of colitis, IL-17A expression was notably increased in CD69+CD103− CD4+ TRM cells." (PMID 35844584, 2022). "CD69+CD103− CD4+ TRM cells are the major source of IL-17A production in the colon of mice with DSS-induced colitis." (PMID 35844584, 2022). "IL-17A expression in CD69+CD103− CD4+ TRM cells was impaired in TIGIT−/− mice during the induction of colitis." (PMID 35844584, 2022). "Decreased ROS production by monocytes and an increased number of CD69-positive monocytes were observed in MPTP-treated rats compared to saline-treated rats during colitis." (PMID 34884737, 2021). "It is also possible that CD69-independent mechanisms contribute to the inhibitory effect of anti-Myl9/12 Ab treatment in DSS-induced colitis." (PMID 33584659, 2020). "Taken together, these data indicated that CD69+ Tregs suppressed chemical-induced colitis in a IL-10 dependent manner." (PMID 30185773, 2018). "Poly(I:C) treatment during T cell transfer colitis attenuates colitis by IFNAR-dependent CD69 induction on T cells, which leads to downregulation of proinflammatory cytokine levels." (PMID 28352268, 2017). "The numbers of activated T cells expressing the earliest inducible cell surface glycoprotein acquired during lymphoid activation, CD69, were analysed after colitis induction." (PMID 25110521, 2014). "CD69 KO mice showed reduced colitis in both acute and chronic DSS-induced colitis models, and CD69 was highly expressed on the infiltrating CD4 T cells in DSS-treated WT mice." (PMID 23785429, 2013). "In order to evaluate the role of CD69 in the development of experimental colitis, acute colitis was induced in CD69 KO and control wild-type (WT) mice by adding 4% DSS to their drinking water." (PMID 23785429, 2013). "The administration of an anti-CD69 antibody also inhibited the induction of the DSS-induced colitis." (PMID 23785429, 2013). "Using two different colitis models we showed that CD69−/− CD4 T cells accumulate preferably in the cLP under the inflammatory conditions." (PMID 23776480, 2013). "In DSS colitis CD69−/− CD4 T cell accumulation in colonic lamina propria (cLP) was associated with increased expression of CCL-1, CXCL-10 and CCL-19 genes." (PMID 23776480, 2013). "The attenuated colitis in CD69 KO mice appeared to be due largely to the reduced infiltration of T cells into the inflamed colon." (PMID 23785429, 2013). "CD69-deficient mice showed increased transcript levels of some chemokine genes, such as CCL-1, CXCL-10 and CCL-19 in steady-state conditions and after colitis induction." (PMID 23776480, 2013). "The treatment of DSS-induced colitis in CD69−/− mice with the mixture of Abs that neutralize CCL-1, CXCL-10 and CCL-19 did not affect the accelerated body weight loss, but it reduced significantly the histopathological severity of the disease." (PMID 23776480, 2013). "Recently CD69 has been suggested to increase the incidence and severity of colitis in a T cell transfer colitis model." (PMID 23785429, 2013). "Experiments with the transfer of WT CD4 T cells into CD69 KO mice restored the induction of colitis." (PMID 23785429, 2013). "A greater infiltration of total (CD8+) and activated (CD69+ CD8+) T lymphocytes was seen in the colitis group and was exacerbated by HFD." (PMID 22073943, 2011). "Activation of CD4+ CD69+ T cells was more related to the presence of colitis, whereas activated B lymphocytes (CD 19+ CD21+) were more frequent in the obese groups." (PMID 22073943, 2011).
colitis (continued). "CD69 and HSF1 deficiency resulted in much more severe colitis in mice, which could be alleviated by the transplantation of CD69+ Tregs but not Tregs from CD69-knockout mice." (PMID 37064870, 2023). "In addition, colitis was successfully induced only in Foxp3YFP-CreCD69fl/fl but not CD69fl/fl mice when DSS was administered for 5 days followed by normal water, highlighting the importance of CD69+ Tregs in the inhibition of colitis." (PMID 37064870, 2023). "Taken together, CD69 is critical for the ability of iTregs to inhibit colitis." (PMID 37064870, 2023). "CD69+CD103− CD4+ TRM cells were the major source of interleukin-17A (IL-17A) production in the colon and TIGIT deficiency protected mice from induction of experimental colitis by reducing IL-17A–producing CD69+CD103− CD4+ TRM cells." (PMID 35844584, 2022). "Moreover, flow cytometry data showed that the number of CD4+CD69+CD103− TRM cells were correlated with disease activity index in DSS-induced colitis." (PMID 35844584, 2022). "CD69+CD103− CD4+ TRM cells could play an important role in controlling DSS-induced colitis by producing IL-17A." (PMID 35844584, 2022). "Notably, our data showed that anti-Myl9/12 Ab treatment ameliorated DSS-induced colitis, and our previous study showed that anti-CD69 Ab treatment ameliorated DSS-induced colitis." (PMID 33584659, 2020). "However, CD69+ T cells from untreated mice with established TNBS-induced colitis were enriched for CD81+ T cells by 2.1–3.2-fold versus CD81− T cells with or without staphylococcal enterotoxin B (SEB) stimulation." (PMID 32332834, 2020). "In the present study, we detected the high expression of Myl9/12 in inflamed tissues from both UC and CD patients, as well as in mice with DSS-induced colitis, and CD69-expressing cells were preferentially located close to Myl9/12-positive vessels at the inflammatory sites." (PMID 33584659, 2020). "Moreover, CD69+ T regulatory cells have been reported to have higher immunosuppressive potential in the mouse model of colitis." (PMID 32431704, 2020). "Therefore, we explored the relevance of CD69+ Tregs to intestinal inflammation in a mouse model of chemically induced colitis." (PMID 30185773, 2018). "It has been demonstrated that a deficiency in CD69 leads to increased production of pro-inflammatory cytokines (such as TNF-α, IFN-γ, and IL-21), reduced FoxP3+ regulatory T-cell function, impaired oral tolerance, and more severe colitis." (PMID 26206376, 2015). "Higher expression levels of IL-10 in the colon may be involved in the protection of CD69 KO mice from severe colitis." (PMID 23785429, 2013). "In this study, we used CD69 KO mice to assess the role of CD69 in a DSS-induced colitis model." (PMID 23785429, 2013). "In DSS colitis model this was at least partially dependent on the increased expression levels of the chemokines CCL-1, CXCL-10 and CCL-19 in the colon of CD69-deficient animals, as neutralization of these three chemokines significantly improved the histopathological picture in colon." (PMID 23776480, 2013). "Severity of the colitis could be ameliorated in DSS-administrated CD69-deficeint mice with the neutralization of CCL-1, CXCL-10 and CCL-19." (PMID 23776480, 2013). "Our data confirmed that the numbers of both CD69+CD103− and CD69+CD103+ CD4+ TRM cells were significantly increased in the colon of DSS-induced colitis, which was associated with more severe disease activities, pointing to the critical role of TRM cells in the development of colitis." (PMID 35844584, 2022). "Therefore, it is possible that inhibiting the induction of CCL2 and CCL4 may reduce the migration of T cells in the colon and protect CD69 KO mice from severe colitis." (PMID 23785429, 2013). "In addition, the higher levels of IL-10 in the colon may be involved in the protection of CD69 KO mice from severe colitis." (PMID 23785429, 2013). "Moreover, more CD4+ T lymphocytes were activated (CD4+ CD69+) in the colitis + HFD animals." (PMID 22073943, 2011).
colitis (continued). "Another study found that the number of CD4+TRM cells in DSS-induced colitis mice was significantly higher than that in normal mice, and the number of CD4+CD69+CD103-TRM cells was positively correlated with the disease activity index." (PMID 40529369, 2025). "Consistent with CXCR6 being the most highly upregulated chemokine, we found that CD69+ CD103+ CXCR6+ CD4+ and CD8+ T cells were expanded in both the cLP and intraepithelial layer in mice with CPI colitis in comparison to control mice." (PMID 37872166, 2023). "Recently, a study showed that the presence of CD4+CD69+CD103+ TRM cells was predictive of disease flares and depletion of TRM cells led to a suppression of colitis activity." (PMID 35844584, 2022). "CD69+CD103− CD4+ TRM cells accounted for 62.9% and 72.5% of IL-17A+ CD4+ T cells in the colon of DSS-induced colitis or control mice, representing the major source of IL-17A production." (PMID 35844584, 2022). "As for colitis, it has been shown that TRM cells are increased in the gut of patients with IBD and have a pro-inflammatory phenotype that CD69+ T cells expressed higher levels of IFNγ, IL-13, IL-17A, and TNF mRNA than CD69− T cells." (PMID 35844584, 2022). "To further confirm the value of CD69+ Tregs in IBD treatment, we applied another model of colitis, T-cell transfer-induced colitis of Rag1−/− mice." (PMID 30185773, 2018). "In antigen-specific colitis models, the transfer of OVA-specific OT-II CD69−/− naïve CD4 T cells into RAG−/− animals followed by oral delivery of OVA protein resulted also in significant body weight loss and severe colitis." (PMID 25759842, 2015). "We have herein demonstrated that both acute and chronic colitis were attenuated in CD69 KO mice, and that the CD69 expressed on CD4 T cells plays an important role in the development of colitis." (PMID 23785429, 2013). "In contrast, CD69+CD103+ CD4+ TRM cells only accounted for 2.2% of IFNγ- and 5.1% of IL-17A–expressing CD4+ T cells in control mice, 6.5% of IFNγ- and 3.9% of IL-17A–expressing CD4+ T cells in DSS-induced colitis, respectively." (PMID 35844584, 2022). "IFNγ expression was not different in CD69+CD103− subset between mice with or without DSS-induced colitis." (PMID 35844584, 2022). "Majority of the CD69+CD103+ CD4+ TRM cells were Foxp3+ Treg cells that more than 70% of Foxp3+ Treg cells were CD69+CD103+ CD4+ TRM cells both in mice with or without colitis." (PMID 35844584, 2022). "The numbers of CD69−CD103− T cells and CD69+CD103+ CD4+ TRM cells expressing IFNγ or IL-17A were similar between mice with or without colitis." (PMID 35844584, 2022). "Similar to chemical-induced IBD, T-cell transfer-induced colitis in Rag1-/- mice were also attenuated by CD69+ Tregs but not CD69−Tregs." (PMID 30185773, 2018). "The findings demonstrate that (i) Ab-mediated IL-10 neutralization leads to progressive colitis with a reduction in Foxp3+ regulatory T cells and increased numbers of CD8+CD44+ memory T cells as well as activated CD4+CD69+ and CD8+CD69+ T cells in uninfected mice." (PMID 27611574, 2016). "Absence of CD69 induced severe intestinal inflammation in DSS-induced colitis and antigen-specific transfer colitis." (PMID 23776480, 2013). "In vivo CD69−/− CD4 T cells accumulate in the intestine in higher numbers than B6 CD4 T cells as observed in competitive homing assay, dextran sodium sulphate (DSS)-induced colitis and antigen-specific transfer colitis." (PMID 23776480, 2013). "Furthermore, treatment of DSS-administrated CD69−/− mice with the mixture of CCL-1, CXCL-10 and CCL-19 neutralizing Abs significantly decreased the histopathological signs of colitis." (PMID 23776480, 2013). "This study showed CD69 as negative regulator of inflammatory responses in intestine as it decreases the expression of chemotactic receptors and ligands and reduces the accumulation of CD4 T cells in cLP during colitis." (PMID 23776480, 2013).
colitis (continued). "In antigen specific colitis model OT-II×CD69−/− CD4 T cells accumulated in cLP with or without antigen presence showing that this effect is only CD69-dependend." (PMID 23776480, 2013). "Cell transfer of wild-type (WT), but not CD69-deficient CD4 T cells, restored the induction of acute colitis in CD69 KO mice, indicating a critical role of CD69 expression in CD4 T cells." (PMID 23785429, 2013). "The DSS-induced colitis was restored by adoptive transfer of WT CD4 T cells, but not CD69-deficient CD4 T cells, to the CD69 KO mice." (PMID 23785429, 2013). "The decreased percentage of CD8+CD69+CD103+ cells might be a result of the infiltration of circulating CD8+ T cells, pointing to the important role of CD4+ TRM cells in the pathogenesis of DSS-induced colitis." (PMID 35844584, 2022). "Notably, our previous study shows that CD69 knockout (KO) mice only develop slight dextran sodium sulphate (DSS)-induced colitis, and that the CD69 expression on CD4 T cells plays important roles in the pathogenesis of DSS-induced colitis." (PMID 33584659, 2020). "Thus, the regulation of the proliferative activity of CD4 T cells may not be the mechanism by which the CD69 on CD4 T cells plays a role in inducing colitis." (PMID 23785429, 2013). "CD69+CD103− CD4+ TRM cells only accounted for 19.1% and 15.0% of Foxp3+ Treg cells in the colon of mice with or without DSS-induced colitis, respectively." (PMID 35844584, 2022). "Although CD69+CD103+ cells accounted for the majority of Treg cells in both colons, TIGIT expression in Treg cells was not different in mice with or without colitis." (PMID 35844584, 2022). "Surprisingly, CD69+CD103− CD4+ TRM cells were the major source of IL-17A and IFNγ in the gut of mice with or without DSS-induced colitis." (PMID 35844584, 2022). "The ligand for CD69 has not been identified, but it is possible that the anti-CD69 mAb may block the interaction between CD69 and putative CD69 ligands, resulting in reduced CD4 T cell migration and attenuated colitis." (PMID 23785429, 2013). "In addition, adoptive cell transfer of CD69+ Treg, but not CD69− Treg or CD69+ Treg from IL10−/− mice, reduced DSS-induced colitis severity in mice, suggesting WPI exposure may increase immune tolerance via induction of Treg with enhanced suppressive capacities." (PMID 36678267, 2023).
Sepsis (24 papers, 2012 to 2025). Sepsis is defined as life-threatening organ dysfunction caused by a dysregulated host response to infection. "A prominent characteristic of sepsis severity was high expression of CD69 on MAIT cells, which was associated with organ dysfunction, lymphopenia and poor outcome." (PMID 40041474, 2025). "Consistently, heatstroke, like sepsis, was associated with significantly larger relative abundance of PD-1+ cells among CD69+CD8+ T cells than in the other two groups." (PMID 40084252, 2025). "Additionally, the ratio of CD3+CD4+CD69+T/CD3+CD8+CD69+T ≤ 0.2697 was an independent risk factor for poor ICU discharge in G- sepsis patients (HR: 0.34 (0.13, 0.88), P=0.026)." (PMID 36703970, 2022). "While other reports shows that CD69+ T helper cells are increased in mouse models of sepsis, this is the first paper that shows this phenomenon in sepsis patients." (PMID 41208955, 2025). "The largest increase in Th proportions in sepsis compared to control samples was in the population of CD69+ naïve CD4+ T cells (1.99log2FC)." (PMID 41208955, 2025). "The seven patients who died within 28 days after the onset of sepsis expressed significantly elevated levels of CD69 on MAIT cells, while slightly lower levels of PD‐1." (PMID 40041474, 2025). "The CD69 high C1 cluster with highest enrichment in sepsis patients was also dominant in fatal cases, septic shock and in patients with a high Δ‐SOFA score." (PMID 40041474, 2025). "The largest proportional increase in sepsis patients compared to controls was evident in CD69+ naïve CD4+ T cells." (PMID 41208955, 2025). "This study examined CD64 expression on neutrophils and CD69 expression on NK cells by flow cytometry in babies who were born preterm (< 37-weeks of gestation) with clinical symptoms of sepsis." (PMID 39978117, 2025). "In COVID-19 patients, however, the absolute number of cytokine-producing CD56bright NK cells or cytotoxic CD56dim NK cells decreased with enhanced NK cell activation characterized by Ki-67, HLA-DR, and CD69, which indicated sepsis." (PMID 38474403, 2024). "The low level of CD3+CD4+CD69+T/CD3+CD8+CD69+T ratio in G- sepsis (versus G+ sepsis) was mainly due to the upregulated CD3+CD8+CD69+ T (%) (CD8+T cell activation) and in part a consequence of the relatively loss of CD4+T(%)(CD4+T suppression)." (PMID 36703970, 2022). "Consistent with a previous report, we observed an increased expression of CD69 on memory CD8+ T cells in the BM as well as in the spleen early during sepsis indicating a systemic activation of CD8+ T cells." (PMID 36148245, 2022). "As the CD3+CD69+T subsets were changed obviously in G- sepsis, we further investigate the prognostic role of CD3+CD69+T subsets in ICU discharge for patients with G- bacterial sepsis." (PMID 36703970, 2022). "The best immune biomarker which differentiated the diagnosis of G- sepsis from G+ sepsis, included activation markers of CD69, human leukocyte antigen DR (HLA-DR) on CD3+CD8+T subset." (PMID 36703970, 2022). "Peritoneal B1 cells decreased within 36 h after sepsis and migrated to spleen and lymph nodes; an increase in CD69+B cells in the spleen, bone marrow, and lymph nodes as early as 24 h after CLP." (PMID 36425582, 2022). "In our sepsis model, vehicle-treated animals demonstrated a significant increase in both frequency of CD69 expression on iNKT cells and serum IFN-γ levels at 10 h after CS injection." (PMID 29720984, 2018). "Within CD44hi memory CD4+ T cells, a distinct CD69+CD43+ population was identified in the setting of sepsis." (PMID 27861506, 2016). "By 72h, both water and alcohol sepsis groups showed significant increase in the frequency of CD44hi CD69+ CD43+ cells above sham controls." (PMID 27861506, 2016). "In the total CD4+ population, CD69 expression increased significantly 24h after sepsis induction in water fed animals." (PMID 27861506, 2016).